PATZ1 (POZ/BTB and AT hook containing zinc finger 1)
Diseases named in the same sentence as PATZ1 in open-access papers (continued):
Sharing a sentence is not in itself a finding about the gene and the disease.
cancer (continued). "Therefore, it is possible to extend the role of PATZ1 on PD-L1 expression also in cancers other than NSCLC." (PMID 37046851, 2023). "Taken together, we suggest that PATZ1 regulates many cancer-related genes." (PMID 33598459, 2021). "The mutational load in cancer-related genes between naïve and primed appears to be largely similar, if not higher in primed hPSC, where additional point mutations were identified in the cancer-related genes EGFR, PATZ1, and CDK12." (PMID 34831467, 2021). "Future experiments are needed to validate such hypothesis and investigate in further details the duplicity of PATZ1 functions, as well as the switch from high to low PATZ1 expression in the context of cancer progression." (PMID 30744101, 2019). "Importantly, at the observed time-window of age, the more aggressive solid variant of PTC was present in 3 out of 14 carcinomas (21%) in RET/PTC1;Patz1+/− mice, compared with 1 out of 12 carcinomas (8%) in RET/PTC1TG;Patz1+/+ mice." (PMID 29584698, 2018). "A similar role could also be played by PATZ1 in neural stem cells, as indicated by our studies in Patz1−/− mice and in cancer stem cells, as suggested by its enriched expression in stem versus non-stem cancer derived cells." (PMID 29186807, 2017). "With regard to cancer, several studies indicated the involvement of PATZ1 in carcinogenesis." (PMID 29137300, 2017). "Since PATZ1 has been described as an inhibitor of cell proliferation in some cancer cell contexts, we would expect that GSCs growing as spheres that express higher levels of PATZ1 compared to GSCs growing in adhesion may proliferate less." (PMID 28938636, 2017). "Moreover, PATZ1 protein is partially or completely delocalized from nucleus to cytoplasm in most of carcinoma samples." (PMID 25595894, 2015). "Strikingly, T cell-specific depletion of PATZ1 leads to increased frequency of Treg cells, while enforced PATZ1 expression impairs Treg cell differentiation, suggesting that PATZ1 might regulate the carcinogenic process at both the cancer cell and microenvironment level." (PMID 37046851, 2023). "In fact, PATZ1 is required for pluripotency maintenance of embryonic stem cells, plays an essential role in the reprogramming of differentiated cells toward stem cells, and governs the self-renewal ability of adult stem cells, including neural and cancer stem cells." (PMID 37046851, 2023). "ZEB1, HES1, NR6A1, PATZ1, PAX4 and MTF1—have a reported oncogenic role in cancer types other than HCC." (PMID 33541355, 2021). "We also identified potential transcriptional factors with known oncogenic roles in HCC, e.g. ZEB1, or in other cancer types, e.g. HES1, NR6A1, PATZ1, PAX4 and MTF1, in GE1-HCC." (PMID 33541355, 2021). "Seven cofactors (TFAP2A, E2F, GSTM1, IL6, PATZ1, MEF2A and GTF2I) identified in two of the five cancer types have general functions in cancers." (PMID 28684851, 2017). "This retrospective case series describes two young adults (32–35 years old) without cancer predisposition or risk factors, diagnosed with EWSR1::PATZ1-fused NEpT." (PMID 40575153, 2025). "KEGG pathway analysis further revealed an enrichment of pathways related to cell cycle and cancer among the differentially expressed target genes in the absence of PATZ1." (PMID 33598459, 2021). "The POZ/BTB and AT-hook-containing zinc finger protein 1 (PATZ1) is a member of the POZ and Kruppel-like (POK) family of architectural transcription factors and is involved in several physiological and pathological processes, including development and cancer." (PMID 29584698, 2018).
cancer (continued). "PATZ1 is a member of the POK (POZ and kruppel-like zinc finger) family, a unique group of transcription factors playing key roles in development and cancer through their involvement in a variety of cellular processes, including cell proliferation, senescence and apoptosis." (PMID 28938636, 2017). "However, the role of PATZ1 in cancer progression remains controversial largely due to lack of genome-wide studies." (PMID 33598459, 2021). "In this case, the effect of PATZ1 was due to its negative feedback loop on IKK/NF-kB signaling, thus preventing cancer cells from over-stimulation by growth factors or inflammatory mediators, and therefore reducing migration/invasion." (PMID 29186807, 2017).
CNS tumors (6 papers, 2021 to 2025). "In conclusion, although the histopathological appearance of EWSR1::PATZ1 gene fusion CNS tumors is diverse, there are consistent imaging features." (PMID 39583630, 2024). "Here, we describe a molecularly distinct subset of predominantly pediatric CNS neoplasms (n = 60) that harbor PATZ1 fusions." (PMID 34417833, 2021). "As EWSR1::PATZ1 fusion CNS tumors might be a distinct entity, this study aims to investigate the imaging features in documented cases to identify common imaging patterns that may aid radiologists in suggesting a diagnosis." (PMID 39583630, 2024). "Imaging features of the EWSR1::PATZ1 gene fusion CNS tumors included in this study." (PMID 39583630, 2024).
neurodegenerative disease (2 papers, 2021 to 2022). A disorder of the central nervous system characterized by gradual and progressive loss of neural tissue and neurologic function. "Interestingly, several genes involved in neurodegenerative diseases, such as PATZ1, SOX-4." (PMID 35746678, 2022).
psychiatric disorder (1 paper, 2021). A disorder characterized by behavioral and/or psychological abnormalities, often accompanied by physical symptoms. "The maintenance of high Patz1 expression in the adult hippocampus, a region that is essential for many forms of learning, memory and mood regulation, suggests that aberrant expression of PATZ1 could contribute to neurological and psychiatric disorders." (PMID 33898458, 2021).
PATZ1 also shares sentences with these, for which no sentence is quoted: infection (9 papers); Ewing sarcoma (7); anaplastic thyroid carcinomas (4); astroblastoma (3); testicular cancer (3); colorectal cancer (2); Viral Infection (2); Acute hepatitis (1); adenocarcinoma (1); anaphylaxis (1); anaplastic carcinomas (1); astrocytoma (1); B cell lymphomas (1); bladder carcinoma (1); Bone Tumours (1); brain neoplasms (1); cardiovascular diseases (1); cervix carcinoma (1); CNS embryonal tumor (1); diffuse large B-cell lymphoma (1); ependymal tumor (1); epilepsy (1); germ cell tumor (1); head and neck squamous cell carcinoma (1); hyperplasia (1); leukemia (1); mastocytoma (1); medulloblastoma (1); non-Hodgkin lymphoma (1); non-small cell lung carcinoma (1).
A further 12 diseases each share a sentence with PATZ1 in 1 paper.